SNHG25 (small nucleolar RNA host gene 25)
Gene: Long non-coding RNA gene on chromosome 17 (64,145,208 to 64,146,810, forward strand). Ensembl gene ENSG00000266402.
Gene Ontology:
Biological process: RNA processing
Cellular component: nucleolus
Diseases named in the same sentence as SNHG25 in open-access papers:
SNHG25 is named in the same sentence as 15 diseases in open-access papers, as found by Europe PMC text mining. Sharing a sentence is not in itself a finding about the gene and the disease. The quoted sentences say what the papers report.
endometrial cancer (3 papers, 2021 to 2025). Primary or metastatic malignant neoplasm involving the endometrium (mucous membrane that lines the endometrial cavity). "Previous studies have also found that SNHG25 can promote the malignancy of endometrial cancer through miRNA sponges, and it can affect the invasion and apoptosis of renal cancer cells by regulating the miR-363-3p-Twist1 interaction." (PMID 40894525, 2025). "Our findings supported SNHG25 as a tumor-promotor in NB, consistent with its role reported in epithelial ovarian cancer and endometrial cancer." (PMID 35821006, 2022). "However, the specific functions of SNHG25 in endometrial cancer (EC) have not been studied yet." (PMID 34789312, 2021).
epithelial ovarian cancer (3 papers, 2021 to 2024). "Interestingly, SNHG25, known for promoting ovarian cancer progression, and TMEM52B, associated with EGFR and E-cadherin modulation and tumor/metastasis suppression, significantly decreased with KPT-9274 treatment." (PMID 38424218, 2024). "Data extracted from the TCGA database imply a role for SNHG25, located in 17q23.3, in ovarian cancer." (PMID 33613753, 2021). "In vitro, functional experiments demonstrated that high expression of SNHG25 promoted proliferation, migration and invasion, and decreased apoptosis, in ovarian cancer cell lines." (PMID 33613753, 2021). "SNHG25 overexpression hinders epithelial ovarian cancer cell apoptosis but increases cell proliferation, migration, and invasion." (PMID 34789312, 2021). "In vitro and in vivo findings demonstrated that SNHG25 promotes the proliferation, invasion and metastasis of ovarian cancer cells, potentially by regulating COMP." (PMID 33613753, 2021). "The role of SNHG25 in ovarian cancer cell migration and invasion was investigated using the scratch assay and transwell cell migration assay." (PMID 33613753, 2021). "Small nucleolar RNA host gene 25 (SNHG25) has been well-studied in epithelial ovarian cancer." (PMID 34789312, 2021). "Small nucleolar RNA host gene 25 (SNHG25), a long noncoding RNA, has been well-studied in epithelial ovarian cancer." (PMID 34789312, 2021). "The present study revealed that SNHG25 was upregulated in EOC tissues and ovarian cancer cell lines, and SNHG25 knockdown decreased the proliferation, migration and invasion of ovarian cancer cells." (PMID 33613753, 2021). "The expression of SNHG25 mRNA was significantly higher in ovarian cancer cell lines (SKOV3, A2780 and HEY and OVCAR3) compared to normal ovarian surface epithelial cells (IOSE80)." (PMID 33613753, 2021). "The role and molecular mechanisms of SNHG25 in epithelial ovarian cancer (EOC) have not been investigated." (PMID 33613753, 2021).
glioma (3 papers, 2023 to 2025). A benign or malignant brain and spinal cord tumor that arises from glial cells (astrocytes, oligodendrocytes, ependymal cells). "Regarding its relationship with cancer, studies have already demonstrated that SNHG25 positively regulates the upregulation of MAP2K2 in glioma cells and tissues by sponging miR-579-5p." (PMID 40894525, 2025). "Small Nucleolar RNA Host Gene 25 (SNHG25) can promote the progression of glioma cells by activating MAPK Signaling." (PMID 37239411, 2023).
COVID-19 (2 papers, 2020 to 2024). A disease caused by infection with severe acute respiratory syndrome coronavirus 2. "MALAT1, NEAT1, and SNHG25 long noncoding RNAs (lncRNAs) were downregulated in mild and severe COVID-19 BAL cells." (PMID 33138195, 2020). "Gene signatures from three lncRNA gene markers (MALAT1, NEAT1, and SNHG25) were found to be downregulated in mild and severe cases of COVID-19, compared to normal controls." (PMID 33138195, 2020). "Further downregulation of MALAT1 and NEAT1 was observed in mild-COVID-19 BAL cells, while SNHG25 was markedly downregulated in both mild- and severe-COVID-19 BAL cells." (PMID 33138195, 2020).
neuroblastoma (2 papers, 2023 to 2025). Neuroblastoma (NB) is the most common solid, extracranial childhood tumor. "However, SNHG25 was proven to function through interaction with protein dyskerin pseudouridine synthase 1 (DKC1) in neuroblastoma cells." (PMID 41387767, 2025). "SNHG25, another non-coding SNORA50C host gene, is highly expressed in neuroblastomas (NBs), and the knockdown of SNHG25 inhibits the proliferation, migration, and invasion of NB cells." (PMID 37907779, 2023).
colorectal cancer (1 paper, 2023). A primary or metastatic malignant neoplasm that affects the colon or rectum. "The functional assays showed that after knocking down SNHG25, the metastatic ability of colorectal cancer cells was significantly reduced." (PMID 37751586, 2023). "Our study proved that SNHG25 acts a pro-metastasis role in colorectal cancer, enriching the theory of the functions of lncRNA in colorectal cancer." (PMID 37751586, 2023). "In addition, chromatin immunoprecipitation (ChIP) assays and promoter luciferase reporter assays revealed that PAX5 could activate the transcription of SNHG25 in colorectal cancer cells." (PMID 37751586, 2023).
glioblastoma multiforme (1 paper, 2025). "Although SNHG25 shows potential as biomarkers in several cancers, limited studies have focused on glioblastoma multiforme." (PMID 41387767, 2025). "Future biomolecular experiments are warranted to study the precise position in IGF2BP2 that SNHG25 (both wild-type and mutant) binds to and the impacts of this binding on recognizing m6A-modified mRNAs in glioblastoma multiforme." (PMID 41387767, 2025). "It will be valuable to screen all proteins that bind with SNHG25 in glioblastoma to study whether SNHG25 interacts with IGF2BP2 and promotes the formation of a complex including SNHG25, IGF2BP2 and other proteins." (PMID 41387767, 2025). "We infer that SNHG25 is likely to function by binding with IGF2BP2 in glioblastoma multiforme." (PMID 41387767, 2025). "An example is the structural change in the lincRNA small nucleolar RNA host gene 25 (SNHG25), which overlaps the binding site of protein insulin like growth factor 2 mRNA binding protein 2 (IGF2BP2) in glioblastoma multiforme." (PMID 41387767, 2025). "The differential expression of SNHG25 and IGF2BP2 suggests their biological function in glioblastoma multiforme." (PMID 41387767, 2025). "Its first mechanism was reported in 2022, and no study has been done regarding the protein binding of SNHG25 in glioblastoma multiforme." (PMID 41387767, 2025).
osteosarcoma (1 paper, 2023). A usually aggressive malignant bone-forming mesenchymal neoplasm, predominantly affecting adolescents and young adults. "SNHG25 was found to be highly expressed in osteosarcoma tissues compared to normal adjacent tissues." (PMID 37278038, 2023). "In this study, we identified a novel osteosarcoma-related LncRNA, SNHG25, one of the most upregulated LncRNAs in osteosarcoma tissues, by analyzing GEO data." (PMID 37278038, 2023). "Survival analysis showed upregulation of SNHG25 expression to indicate poor prognosis in patients with osteosarcoma." (PMID 37278038, 2023). "Wound healing and transwell assays indicated that SNHG25 knockdown inhibited osteosarcoma cell migration and invasion." (PMID 37278038, 2023). "More importantly, SNHG25 knockdown dramatically suppressed the proliferation, migration, and invasion of osteosarcoma cells, and promoted their apoptosis in vitro." (PMID 37278038, 2023). "Subcellular fractionation assays showed SNHG25 to be mainly expressed in the cytoplasm of osteosarcoma cells." (PMID 37278038, 2023). "The heatmap indicated the SNHG25 expression level to be dramatically elevated in osteosarcoma tissues compared to normal adjacent tissues (n=10)." (PMID 37278038, 2023). "We identified aberrant expression of LncRNA SNHG25 (small nucleolar RNA host gene 25) in osteosarcoma and analyzed the molecular mechanisms by which it regulates osteosarcoma progression." (PMID 37278038, 2023). "In this study, SNHG25 was found to function as an oncogene by promoting osteosarcoma cell proliferation, invasion, and migration via the miR-497-5p/SOX4 axis." (PMID 37278038, 2023). "SNHG25 was determined to function as an oncogene by promoting osteosarcoma cell proliferation, invasion, and migration through the miR-497-5p/SOX4 axis." (PMID 37278038, 2023). "More importantly, the Log-rank analysis confirmed increased SNHG25 expression to be an unfavorable prognostic factor for osteosarcoma patients (HR=2.20, 95% CI: 1.08–4.48, P=0.03)." (PMID 37278038, 2023). "In addition, SNHG25 expression was higher in osteosarcoma cells (MG-63, U-2OS, and Saos-2) than in normal osteoblasts." (PMID 37278038, 2023). "SNHG25 functions as a sponge for miR-497-5p in osteosarcoma cells." (PMID 37278038, 2023). "Upregulation of SNHG25 expression indicated poor prognosis in patients with osteosarcoma, which showed that SNHG25 may serve as a potential therapeutic target and prognostic biomarker in osteosarcoma." (PMID 37278038, 2023). "Next, we sought to determine whether SNHG25 promotes osteosarcoma progression through SOX4." (PMID 37278038, 2023). "Therefore, SNHG25 functions as a sponge for miR-497-5p in osteosarcoma cells." (PMID 37278038, 2023). "However, the role of SNHG25 in osteosarcoma remains unclear." (PMID 37278038, 2023).
uterine corpus endometrial carcinoma (1 paper, 2021). A endometrial carcinoma (disease) that involves the body of uterus. "The SNHG25 level was increased in uterine corpus endometrial carcinoma tissues compared with normal tissues." (PMID 34789312, 2021). "Through the TCGA database, SNHG25 was found to be one of the top 10 overexpressed lncRNAs in uterine corpus endometrial carcinoma." (PMID 34789312, 2021).
cancer (8 papers, 2021 to 2025). A tumor composed of atypical neoplastic, often pleomorphic cells that invade other tissues. "Specifically in COAD, low expression of SNHG25 has been closely associated with reduced metastatic potential, indicating its pathological relevance in this cancer type." (PMID 40894525, 2025). "SNHG25, a member of the lncRNA family, has been proven to promote the proliferation and migration of cancer cells in COAD." (PMID 40894525, 2025). "Given that the upregulation of SNHG25 significantly enhances cancer cell invasiveness, two drugs, dabrafenib_1373 and OSI-027_1594, which exhibit significant negative correlations with SNHG25 expression, were screened as therapeutic candidates." (PMID 40894525, 2025). "Previous studies have highlighted lncRNAs' key role in cancer, but the exact function of lncRNA SNHG25 in COAD remains unclear." (PMID 40894525, 2025). "Additionally, ISH assays displayed higher SNHG25 expression in cancer tissue compared to adjacent normal tissue." (PMID 37751586, 2023). "Thus, the miR-497-5p/FASN axis operated as the downstream effector pathway through which SNHG25 played cancer-promoting roles in EC." (PMID 34789312, 2021). "AC10889.1, TTTY15, XIST, AC006157.1, PAX8-AS1, SNHG25, and JPX were mainly involved in cancer development." (PMID 33924951, 2021).
tumor (8 papers, 2021 to 2025). "Enrichment analysis revealed that high SNHG25 expression was associated with oxidative phosphorylation, indicating enhanced mitochondrial metabolism that supports tumor growth and survival." (PMID 40894525, 2025). "In this study, we aimed to elucidate the clinical significance of SNHG25 in EC and determine the regulatory activities of SNHG25 on the tumor-associated EC phenotype." (PMID 34789312, 2021). "Functionally, SNHG25 deficiency resulted in tumor-repressing activities in EC cells by decreasing cell proliferation, migration, and invasion and promoting cell apoptosis." (PMID 34789312, 2021). "In this study, we aimed to elucidate the clinical significance of SNHG25 in EC and determine the regulatory activity of SNHG25 on the tumor-associated EC phenotype." (PMID 34789312, 2021). "SNHG25 deficiency resulted in tumor-repressing activities in EC cells by decreasing cell proliferation, migration, and invasion and promoting cell apoptosis." (PMID 34789312, 2021). "Immune infiltration analysis showed that SNHG25 was significantly associated with a variety of immune cell subtypes (e.g., macrophages and neutrophils) and might be involved in the remodeling of the tumor immune microenvironment." (PMID 40894525, 2025). "In vivo, downregulation of SNHG25 inhibited the growth (tumor volume) of subcutaneous xenografts in nude mice." (PMID 33613753, 2021). "SNHG25 is a newly discovered LncRNA involved in tumour progression located on chromosome 17q23.3." (PMID 37278038, 2023). "In addition, the results of Gene Set Enrichment Analysis (GSEA) showed that the expression of SNHG25 in CRC cells was related to some tumor metastasis gene sets (ALONSO_METASTASIS_EMT_UP, BIDUS_METASTASIS_UP and CHANDRAN_METASTASIS_TOP50_UP)." (PMID 37751586, 2023). "Notably, analysis of clinical data from CRC patients revealed that elevated SNHG25 expression correlated with tumor progression and a worse prognosis." (PMID 37751586, 2023). "It is known that the SNHG family, including SNHG25, can participate in tumor progression." (PMID 33613753, 2021). "Additionally, the downregulation of SNHG25, overexpression of miR-497-5p, and reduction of FASN were confirmed in sh-SNHG25-transfected tumor xenografts." (PMID 34789312, 2021). "The results indicated that SNHG25 expression was significantly negatively related to the expression of Merck18, CD8, and CAF, while it showed a significant positive relation with the expressions of myeloid-derived suppressor cell (MDSC) and tumor-associated macrophage (TAM) M2 (p < 0.01)." (PMID 40894525, 2025). "Furthermore, the function of SNHG25 depletion in impairing tumor growth in vivo was confirmed." (PMID 34789312, 2021). "Furthermore, the function of SNHG25 depletion in impairing tumor growth in vivo was validated." (PMID 34789312, 2021).
SNHG25 also shares sentences with these, for which no sentence is quoted: ovarian cancer (2 papers); clear cell renal cell carcinoma (1); prostate carcinoma (1); renal carcinoma (1).